PLK1 (polo like kinase 1)
Diseases named in the same sentence as PLK1 in open-access papers (continued):
Sharing a sentence is not in itself a finding about the gene and the disease.
cancer (continued). "Here, by defining the essential role of G6PD activation in Plk1-mediated cell cycle control and cancer progression, our results reinforced the importance of crosstalk between cell mitosis and metabolic changes and, in particular, the significance of metabolic inputs in determining the cell fate." (PMID 29138396, 2017). "Plk1 and RSK1 formed a regulatory feedback mechanism in MKN45 and MKN74 CSC-like cells to help resist the loss of RSK1 functions, which differed from the mechanism in the cancer cells." (PMID 28430578, 2017). "Collectively, our findings established the role of Plk1 in coordinating cell cycle progression with biosynthesis and thus substantially enriched the current understanding of functions of this kinase in the pathways to cancer development." (PMID 29138396, 2017). "Polo-like kinase 1 (PLK1) has been suggested to serve as an oncogene in most human cancers." (PMID 28724602, 2017). "Recently, a study demonstrated that siRNA-based inhibition of PLK-1 causes a notable reduction in the proliferation of cancer cells but not in the proliferation of normal cells." (PMID 28415805, 2017). "We conclude that PLK1 inhibition blocks cell cycle progression in neuroblastic cells by blocking PLK1 canonical regulatory function at the G2/M transition as well as cancer cell-specific blockage of G1/S transition occurring presumably via de-repression of RB1-associated gene expression." (PMID 28036269, 2017). "A reduction in PLK-1 expression may also enhance the sensitivity of cancer cells to anti-cancer agents such as cisplatin." (PMID 28415805, 2017). "Some studies on EOC, SCCC and NSCLC found miR-100 was significantly decreased in cancer tissues in comparison to healthy people, which appeared that low miR-100 was a poor prognostic biomarker by targeting PLK1 in patients and some researches in HCC, CRC and ESCC hold the similar view." (PMID 28977982, 2017). "Inhibition of PLK1 and KSP caused cell-cycle arrest and induction of apoptosis in cancer cells." (PMID 34322587, 2017). "Recently, BI 6727 was found to inhibit PLK1 activity selectively in many cancers." (PMID 29228610, 2017). "In cancer cells, the knock down or inhibition of PLK1 results in a variety of biological effects, including G2/M accumulation, spindle defects, chromosomal alignment defects, mitotic slippage, apoptosis, senescence, and defective centrosome maturation or separation." (PMID 27384992, 2016). "These developments provide a strong validation for Plk1 as a cancer drug target." (PMID 27874094, 2016). "PLK1 is overexpressed in a variety of human tumors and its expression level often correlates with increased cellular proliferation, enhanced metastatic potential, and poor prognosis in cancer patients." (PMID 27003818, 2016). "For these reasons, Plk1 is recognized as a prime target for anti-cancer drug development." (PMID 27874094, 2016). "Moreover, FOXC2 is also an important downstream player of PLK1 in cancer cells with stem cell properties." (PMID 27064522, 2016). "Over-expression of PLK-1 in cancers is thought to portend an adverse prognosis." (PMID 26754547, 2016). "Furthermore, we also used an androgen-refractory cancer of the prostate (ARCaP) model to verify the role of PLK1 in induction of EMT." (PMID 27003818, 2016). "In the present study, we determined whether the inhibition of PLK1 enhanced the cytotoxic effects of radiation by modulating the cell cycle phase of cancer cells." (PMID 26503893, 2015). "Thus, the inhibition of PLK-1, negatively affects cancer cell proliferation and reduces tumor growth." (PMID 26557691, 2015). "Interestingly, various types of cancer cells are shown to be addicted to a high level of Plk1, and the reversal of Plk1 addiction appears to be an effective strategy for selectively killing cancer cells, but not normal cells." (PMID 26500787, 2015). "Hence, PLK-1 is the most efficient, validated drug target to inhibit cancer growth with the maximum selectivity index." (PMID 26557691, 2015).
cancer (continued). "Furthermore, many studies have proven that overexpression of PLK-1 is not only related to tumorigenesis but also highlighted in the poor prognosis of cancer." (PMID 26557691, 2015). "Plk1 has predictive and prognostic value for cancer patients." (PMID 26317649, 2015). "The elevated level of PLK1 in cancer cells could reflect a larger number of targets for PLK1i per cell." (PMID 25871386, 2015). "Not surprisingly, Plk1 overexpression appears to be tightly associated with aggressiveness and poor prognosis of various types of human cancers." (PMID 26500787, 2015). "Inhibitors of PLK1 have been developed for potential human cancer therapy." (PMID 25574601, 2015). "We aimed to show that there is a relationship of PLK1 to FOXM1 in cancer samples." (PMID 26576650, 2015). "PLK1 is overexpressed in several types of cancer and correlates with high tumor grades." (PMID 26085038, 2015). "Furthermore, the expression of PLK1 in untransformed cells is much lower, which makes PLK1 a suitable target for the development of cancer-specific small molecule drugs." (PMID 25574601, 2015). "Our quantitative real-time PCR and Western blot analyses revealed a regulation of Plk1 at the transcriptional level by SAHA, because in cancer and non-cancer cells Plk1 mRNA levels were statistically significantly reduced by SAHA (alone and in combination with SBE13)." (PMID 26317649, 2015). "Overexpression of PLK1 in a variety of cancers had been observed." (PMID 26090465, 2015). "This suggests that PLK1 is an essential regulator of NEK2A in cancer cells." (PMID 25705694, 2015). "Additionally, critical roles in many aspects of cancer cell growth, proliferation, metastasis, and drug resistance have been assigned to some of these centrosomal kinases, such as polo-like kinase 1 (PLk1) and Aurora-A kinase." (PMID 25705694, 2015). "A wide range of human cancers have been screened to validate PLK-1 inhibition during tumor growth." (PMID 26557691, 2015). "Under these conditions, the reversal of Plk1 addiction may be sufficient for triggering cancer cell-selective mitotic block and apoptotic cell death, as has been demonstrated by the reversal of oncogene addictions." (PMID 26500787, 2015). "Therefore, we set out to examine cell fate in response to Plk1 inhibitors using a single-cell-based time-lapse microscopy approach that previously revealed extensive intra- and interline variation when cancer cells are exposed to microtubule toxins." (PMID 26472023, 2015). "We herein investigated whether PLK1 blockade enhanced the cytotoxic effects of radiation by modulating cell cycle phases of cancer cells using the novel small molecule inhibitor of PLK1, TAK-960." (PMID 26503893, 2015). "Therefore, this work provides clear-evidence that PLK-1 is exclusively considered as the most promising cancer drug target with minimal adverse complications." (PMID 26557691, 2015). "Based upon these results, we hypothesize that Plk1 overexpression impairs the IR-induced G2 checkpoint and then leads to mitotic catastrophe in cancer cells in the presence of NU7441." (PMID 25714019, 2015). "PLK1 is an important oncogene and drug target in many cancer entities." (PMID 24767679, 2014). "STK31 might serve as a potential target for cancer treatment given that inhibitory compounds targeting cell cycle kinases such as Polo-like kinase 1, Aurora-A and Aurora-B have been quite successful in treating cancers." (PMID 24667656, 2014). "Plk1 has predictive and prognostic value for patients with diverse cancers." (PMID 24810255, 2014).
cancer (continued). "In our current report we further explore this hypothesis, using several novel experimental small-molecule inhibitors of Plk1 and anti-Plk1siRNA to examine the cellular consequences of prolonged or transient mitotic arrest, specifically in cancer cells." (PMID 25365521, 2014). "Therefore, PLK1 expression shows a close relationship with cancer development and its small molecule inhibitors have been used in clinical trials in advanced cancer patients." (PMID 25019081, 2014). "In our earlier studies, we could already show that inhibition of Plk1 sensitizes cancer cells to anti-neoplastic drugs." (PMID 24810255, 2014). "Polo-like kinase-1 (Plk1) plays a crucial role in cell proliferation and the inhibition of Plk1 has been considered as a potential target for specific inhibitory drugs in anti-cancer therapy." (PMID 25211362, 2014). "Due to its overexpression in many human tumors, Plk1 has been extensively studied as a target for anti-cancer therapy and a number of compounds that either act as ATP-competitive inhibitors or interfere with Polo-box domain functions of Plk1 have already been identified." (PMID 24901228, 2014). "Earlier studies could show that Plk1 inhibition by siRNAs or ASOs elevates drug sensitivity of cancer cells." (PMID 24810255, 2014). "Thus, we demonstrate for the first time that Plk1 inhibition using SBE13 enhances the effects of Enzastaurin in cancer cells." (PMID 24810255, 2014). "This would lead to altered expression profiles in cancer tissues and might partly explain the detected variability of PLK1 expression in different cancer entities." (PMID 24767679, 2014). "For that reason, the combination of Plk1 and PKCβ inhibitors might be a promising tool in cancer therapy." (PMID 24810255, 2014). "Moreover, though PLK1 expression was correlated with metastasis in many types of carcinoma, there was less relationship between PLK1 expression and HCC metastasis, including lymphatic metastasis and extrahepatic metastasis." (PMID 25019081, 2014). "PLK1 is a protooncogene overexpressed in a variety of human cancers." (PMID 24159333, 2013). "There have been very few attempts to delineate the potential role of Plk1 in cell-cycle and cancer." (PMID 23967120, 2013). "Depletion of PLK1 in cancer cells in vitro has been demonstrated to inhibit proliferation." (PMID 23658603, 2013). "To date, overexpression of PLK1 has been observed in various human cancers." (PMID 24349352, 2013). "Together, exploitation of the novel Plk1 mediated functions specified in this study may open new avenue for cancer therapeutics." (PMID 23967120, 2013). "Several Plk1 inhibitors have been developed and tested for the cancer treatment." (PMID 24216699, 2013). "Thus, it is not surprising that known factors of the checkpoint recovery pathway, including Plk1, Aurora A and Wip1, were found to be upregulated in cancers in correlation with more aggressiveness and poor prognosis." (PMID 23618492, 2013).
cancer (continued). "In other cancers, PLK1 has been reported to be a functional target of miR-100." (PMID 23151088, 2012). "PLK1 is a marker of cellular proliferation, and plays important roles in cancer development." (PMID 22838965, 2012). "Previous data suggest that depletion of PLK1 induces apoptosis in cancer cells." (PMID 23056340, 2012). "Because PLK1 plays a more important role in the division of cancer cells, we speculate beta-carboline compounds may preferentially inhibit the growth of cancer cells by targeting PLK1." (PMID 23056340, 2012). "The distinct apoptotic responses of HeLa and MRC5 cells to beta-carboline compounds could explain the selectivity of PLK1 inhibitors toward cancer cells." (PMID 23056340, 2012). "The difference makes PLK1 an ideal anti-cancer target, because PLK1 inhibitors may selectively kill cancer cells." (PMID 23056340, 2012). "It has been reported that the overexpression of PLK1 could affect growth, apoptosis, metastasis and chemo-or radioresistance in human cancers." (PMID 22246341, 2012). "In addition to promoting proliferation of healthy cells, Plk1 also plays an important role in cancer development." (PMID 23227884, 2012). "Moreover, the immunohistoligical study showed that PLK-1 protein was overexpressed in NSCLC tissues in patients at progressed stages of cancer (postsurgical stage ≥II) and in patients with poorly differentiated NSCLCs." (PMID 21884621, 2011). "Consequently, our preclinical applications suggest that PLK-1 siRNA is a promising tool for cancer therapy." (PMID 21884621, 2011). "Based on this, PLK1 inhibitors may need to be used in combination with an approved cancer drug in order to be clinically useful." (PMID 22248814, 2011). "In the future, these analyses could help to design drugs that block the interaction between PLK1 and its partners to block cell division for the treatment of diseases like cancer." (PMID 20711360, 2010). "Thus, it appears that cancer cells die more efficiently upon Plk1 inhibition, as compared to normal cells." (PMID 20886032, 2010). "Feedback mechanisms, in which mitotic kinases can silence DNA damage checkpoints, may thus explain why Plk1 and Aurora A are frequently overexpressed in cancers and may form a rationale for including inhibitors of such mitotic kinases during cancer treatment." (PMID 20126263, 2010). "This is in contrast to anti-Plk1 microinjection study in human fibroblasts, which showed predominantly a G2 phase-like arrest phenotype in primary cells, despite a clear mitotic arrest in cancer (HeLa) cells." (PMID 20886032, 2010). "Indeed, Plks are frequently overexpressed in tumor cells with uncontrolled proliferation and genome instability, and high level of Plk1 is predictive of a bad prognosis in several cancers." (PMID 20098491, 2010). "With the development of more specific anti-cancer drugs, we decided to investigate the potential of the Polo-like kinase 1 (PLK1) inhibitor BI 2536 as a potential drug to eliminate proliferating cells from in vitro cultures containing terminally differentiated cardiomyocytes." (PMID 20886032, 2010). "Together with the facts that numerous cancer cells show increased Plk1 expression, these results further supported that Plk1 could be a specific anti-cancer target." (PMID 20886032, 2010). "There are several ongoing clinical trials on other cancers using PLK1 inhibitors; some of these may be potential therapeutic agents in RB as well." (PMID 20664703, 2010). "Several strategies of inhibiting Plk1 activity have thus been tested in cancer therapeutic trials." (PMID 19161615, 2009).
cancer (continued). "Because of secondary effects in normal cells and also because of resistance of cancer cells to such treatments, new targets have been explored, leading to the development of inhibitors of mitotic kinases such as Plk1 or Aurora, or of motor proteins such as Eg5." (PMID 19243593, 2009). "Since Plk1 is considered as a "proto-oncogene", inhibition of Plk1 could be an effective treatment for cancers." (PMID 19161615, 2009). "With regard to tumorigenesis, it is worth noting that polo-like kinase 1 (PLK-1), a mitotic cyclin-independent serine-threonine kinase that is believed to be involved in the pathogenesis of numerous carcinomas, has attracted much attention as a potential therapeutic target." (PMID 19775446, 2009). "Currently, considerable effort is being expended to obtain Plk1 inhibitors for use in cancer therapy, and it may be possible to exploit these efforts in the future to generate new, much needed antiparasitic agents." (PMID 17662039, 2007). "Additionally, it may promote cancer by adsorbing certain miRNAs, thereby regulating the expression of downstream genes, or by activating specific pathways, such as the Aurora A/PLK1 pathway." (PMID 41282486, 2025). "Over the past decade, several Plk1 inhibitors have entered into clinical trials for many different tumor types to evaluate their anti-tumorigenic activity and safety, and these Plk1 inhibitors exhibit promising efficacy and a good safety profile in many of these cancer types." (PMID 40166466, 2025). "Consequently, PLK1 could be an attractive therapeutic target to abolish this cancer-promoting signaling node." (PMID 39831777, 2025). "Moreover, PLK1 acts as a tumor promoter in a variety of cancers and modulates autophagy." (PMID 40517136, 2025). "Polo-like kinase 1 [plk1] is typically considered a proto-oncogene relevant for cell cycle progression, which is reflected in the expression profiles of different types of cancer, where it is commonly overexpressed and shows strong correlation with carcinogenesis events and checkpoint dysregulation." (PMID 40430225, 2025). "Besides, PLK1 has been proved to be involved in homologous recombination, and PLK1 expression has been positively correlated with homologous recombination deficiency (HRD) scores in various cancers, including EOC." (PMID 41458961, 2025). "Indeed, several genes—such as BMYB, FOXM1, polo-like kinase 1 (PLK1), Aurora kinase A (AURKA), and CCNB1—regulated and suppressed by the DREAM complex are overexpressed in various cancers and are associated with a poor cancer prognosis." (PMID 39796178, 2025). "Also, we showed that a PLK1 inhibitor, developed for cancer treatments, reduced growth and neoblast-like cell activity, illustrating the potential for targeting liver fluke kinases associated with neoblast-like cells with drugs, providing new routes to drug development." (PMID 41329781, 2025). "In addition, PLK1 can also coordinate cancer progression by influencing metabolic reprogramming." (PMID 40612941, 2025). "Moreover, PLK1-overexpressing cells exhibit an enhanced reliance on extracellular nutrients to sustain their growth, suggesting that both de novo serine biosynthesis and serine uptake are potential therapeutic targets for cancers." (PMID 40475404, 2025). "Also, of potential therapeutic interest, our gene enrichment study identified in acid-exposed cancer cells an increase in the signaling pathway driven by POLO-like 1 kinase (PLK-1) that is known to support mitotic entry following recovery from DNA damage in polyploid cells." (PMID 38366255, 2024).